SLC17A2 (solute carrier family 17 member 2)
Description:
Acts as a membrane potential-dependent organic anion transporter, the transport requires a low concentration of chloride ions (By similarity). Mediates chloride-dependent transport of urate (By similarity). Can actively transport inorganic phosphate into cells via Na(+) cotransport (By similarity).
Synonyms: NPT3
Tractability: Antibody: its Gene Ontology location is reachable by antibodies, with high confidence; UniProt places it where antibodies can reach, with medium confidence; UniProt predicts a signal peptide or a membrane-spanning region.
Target class: Transporter; SLC superfamily of solute carriers; Electrochemical transporter; SLC17 phosphate and organic anion transporter family
Gene: Protein-coding gene on chromosome 6 (25,906,892 to 25,930,815, reverse strand). Ensembl gene ENSG00000112337.
Subcellular location: Apical cell membrane
Gene Ontology:
Molecular function: sodium:phosphate symporter activity; transmembrane transporter activity; urate transmembrane transporter activity
Biological process: phosphate-containing compound metabolic process; sodium ion transport; sodium ion transmembrane transport; transmembrane transport; urate transport
Cellular component: apical plasma membrane; membrane; plasma membrane
Genetic constraint (gnomAD): Loss-of-function variants: 33 observed, 46.81 expected, observed/expected ratio (o/e) 0.7, 90% interval 0.53 to 0.94. The upper end of that interval is the gene's LOEUF score, 0.94, which puts it in group 4 of 6, group 1 being the genes least tolerant of losing a copy. Missense variants: 480 observed, 579.76 expected, observed/expected ratio (o/e) 0.83, 90% interval 0.77 to 0.89. Synonymous variants: 219 observed, 213.91 expected, observed/expected ratio (o/e) 1.02, 90% interval 0.92 to 1.14.
Homologues: Orthologues: chimpanzee SLC17A2 (99% identical), macaque SLC17A2 (97% identical), pig SLC17A2 (90% identical), rabbit SLC17A2 (89% identical), mouse Slc17a2 (88% identical), guinea pig SLC17A2 (86% identical), rat Slc17a2 (79% identical), zebrafish si:ch1073-513e17.1 (38% identical), zebrafish slc17a5 (36% identical), Drosophila melanogaster Picot (31% identical), Drosophila melanogaster CG6978 (30% identical), Drosophila melanogaster CG15096 (30% identical), and 45 more. Paralogues in human: SLC17A4 (59% identical), SLC17A3 (55% identical), SLC17A1 (48% identical), SLC17A5 (37% identical), SLC17A8 (32% identical), SLC17A6 (32% identical), SLC17A7 (31% identical), SLC17A9 (23% identical), SLC37A1 (19% identical), SLC37A2 (18% identical), SLC37A4 (17% identical), SLC37A3 (14% identical).
Diseases named in the same sentence as SLC17A2 in open-access papers:
SLC17A2 is named in the same sentence as 9 diseases in open-access papers, as found by Europe PMC text mining. Sharing a sentence is not in itself a finding about the gene and the disease. The quoted sentences say what the papers report.
atherosclerosis (1 paper, 2022). A disease characterized by the build-up of fatty material and calcium deposition in the arterial wall resulting in partial or complete occlusion of the arterial lumen. "Another large study evaluating 12 SNPs in RA patients, identified novel associations between subclinical atherosclerosis and variants in SLC17A2 (rs17526722), PPCDC (rs1867148), COL4A1 (rs496916) and SLCA13 (rs515291) genes, that may constitute new candidate risk loci for CVD in RA89." (PMID 35680906, 2022).
gout (1 paper, 2018). A condition characterized by painful swelling of the joints, which is caused by deposition of urate crystals. "SLC17A2 was a novel gene that was found to be associated with the pathogenesis of gout (OR = 0.83, PFDR = 0.017)." (PMID 29497127, 2018). "In addition, five genes (PKD2, SLC2A9, SLC17A1, SLC17A4 and SLC17A2) were determined to influence the risk of gout (all PFDR < 0.05)." (PMID 29497127, 2018). "In addition, these two pathways were further associated with the pathogenesis of gout (PFDR = 1.08E-08 and 2.66E-03, respectively) in the Chinese population and a novel gout-associated gene, SLC17A2, was identified (OR = 0.83, PFDR = 0.017)." (PMID 29497127, 2018). "SLC17A2 was identified as a novel gene that influenced the risk of gout." (PMID 29497127, 2018). "In addition, we identified a novel gout-associated gene, SLC17A2, in this study." (PMID 29497127, 2018). "Regarding SLC17A2, its protein levels were measured among gout patients, hyperuricemia patients and healthy controls by performing Western blot." (PMID 29497127, 2018). "In the present study, SLC17A2 was found to be associated with gout risk either in the presence of hyperuricemia or not, and it variant played a protective role against gout." (PMID 29497127, 2018). "Thus, SLC17A2 might influence the development of gout by changing its expression." (PMID 29497127, 2018).
hyperuricemia (1 paper, 2018). An abnormally high level of uric acid. "In our study, the mRNA expression and protein levels of SLC17A2 between healthy individuals and hyperuricemia patients were significantly different, also suggesting potential correlation between this variant and mRNA expression." (PMID 29497127, 2018). "The result showed the SLC17A2 protein level was higher in hyperuricemia patients than in others, which was consistent with our previous result in mRNA level." (PMID 29497127, 2018). "However, the transcription levels of both SLC17A2 and SLC5A6 were significantly different between the hyperuricemia patients and healthy subjects, suggesting that these two genes potentially affect serum urate levels." (PMID 29497127, 2018).
cancer (1 paper, 2021). A tumor composed of atypical neoplastic, often pleomorphic cells that invade other tissues. "Among 17 differentially methylated genes in aggressive cases, a few genes, such as SLC17A2 and OR51A4, were not investigated previously for human cancers." (PMID 33450964, 2021).
SLC17A2 also shares sentences with these, for which no sentence is quoted: Fanconi renotubular syndrome 2 (1 paper); metabolic syndrome (1); nephrolithiasis (1); osteoporosis (1); tumours (1).